CYP1B1 (cytochrome P450 family 1 subfamily B member 1)
Diseases named in the same sentence as CYP1B1 in open-access papers (continued):
Sharing a sentence is not in itself a finding about the gene and the disease.
infection (10 papers, 2016 to 2025). The state of being infected such as from the introduction of a foreign agent such as serum, vaccine, antigenic substance or organism. "Lentiviral infection of both cell lines with the two polymorphic forms of CYP1B1 (wild-type V432 and variant L432) or with an empty vector (p15) generated two series of isogenic cell lines, the CYP1B1-WT, the CYP1B1-VAR and the p15 control cell lines." (PMID 32565541, 2020). "CYP1B1 was knocked down in MC38 cells using lentiviral infection and western blot was used to analyze protein expression." (PMID 37059712, 2023). "Moreover, a strong oxidative stress response in the form of increased expression of metallothioneins and other antioxidant enzymes, as well as the upregulation of xenobiotic metabolism (CYP1A1 and CYP1B1) were found following infection with C. concisus UNSWCD." (PMID 27677841, 2016). "Furthermore, the infection led to the upregulation of CYP1A1 and CYP1B1 levels, which are downstream target proteins in AhR signaling." (PMID 40142473, 2025).
cardiovascular diseases (6 papers, 2011 to 2024). "Mechanistically, CYP1B1 contributes to cardiovascular disease through oxidation of AA into cardiotoxic mid-chain HETEs metabolite and the formation of superoxides." (PMID 29426916, 2018). "The role of CYP1B1 in the development of cardiovascular diseases is well established." (PMID 39188949, 2024).
metabolic disease (6 papers, 2020 to 2025). A congenital disorder (due to inherited enzyme abnormality) or acquired (due to failure of a metabolically important organ) disorder resulting from an abnormal metabolic process. "Specifically, our observations raise the possibility that CYP1B1 could represent a therapeutic target for the treatment of selected metabolic diseases." (PMID 36518674, 2022). "In addition, CYP1B1 also plays a role in endogenous metabolic pathways in metabolic disorders." (PMID 41267622, 2025). "CYP1B1 is a member of the CYP superfamily and crucial for endogenous metabolic pathways regulation and is expected to be a therapeutic target for the treatment of metabolic diseases." (PMID 36418939, 2022).
bacterial infection (3 papers, 2022 to 2025). "In this article, we shortlisted activated target genes in monocytes during acute bacterial infection, including VNN1, NLRC4, CYP1B1, PFKFB3, LILRA5, NFKBIA or NFKBIZ." (PMID 40581066, 2025). "Other monocyte informative genes were also activated in patients with bacterial infection including NLRC4, CYP1B1, PFKFB3, LILRA5, NFKBIA, and NFKBIZ." (PMID 40581066, 2025). "In this study, flumequine, an antibacterial agent used to treat bacterial diseases, tended to increase the expression of CYP1A1, CYP1B1, CYP2B4, CYP2F2, and CYP4B1 following administration at a 4× dose compared to a 1× dose." (PMID 41227456, 2025).
neurodegenerative disease (3 papers, 2011 to 2025). A disorder of the central nervous system characterized by gradual and progressive loss of neural tissue and neurologic function. "Association of PDIA5 and BIRC6 (as well as PSMB7 and CYP1B1 in the Salt Lake City population) with POAG indicates that adult-onset glaucoma belongs to the same category of late onset neurodegenerative diseases." (PMID 21655191, 2011). "CYP1B1 is known to regulate stem cell senescence and mitochondrial dysfunction, which are critical factors in neurodegenerative diseases." (PMID 39812050, 2025).
renal diseases (3 papers, 2019 to 2023). "In this study, we investigated the presence of a particular miRNA, miR-27b-3p, which is responsible for the regulation of CYP1B1 and is involved in renal diseases." (PMID 37371125, 2023). "While Cyp1b1 has been shown to have a protective role against cardiac and renal diseases in females, it aggravates the pathogenesis of these diseases in males, due to the action of this enzyme on estrogen and testosterone, respectively, as shown by ovariectomy and castration studies." (PMID 31058102, 2019).
adenocarcinoma (2 papers, 2009 to 2021). A common cancer characterized by the presence of malignant glandular cells. "Moreover, CYP1B1 was highly expressed in grade III (59/100, 59.0%) adenocarcinomas compared to grade II (24/100, 24.0%) adenocarcinomas and grade I adenocarcinomas (8/100, 8.0%)." (PMID 34636736, 2021).
retinopathy (2 papers, 2014 to 2022). "Our results point to the involvement of Cyp1a2 and Cyp1b1 in the pathogenesis of AMD-like retinopathy in OXYS rats." (PMID 25132985, 2014).
autosomal recessive disease (1 paper, 2020). Autosomal recessive form of disease. "PCG has been traditionally viewed as an autosomal recessive disease caused by homozygous or compound heterozygous mutations in a major gene, CYP1B1, which account for 30-50% of cases worldwide." (PMID 32152063, 2020).
benign tumor (1 paper, 2015). "In the present study, we confirmed the high CYP1B1 immunoreactivity in 53 primary samples and 14 metastatic tissue samples from patients with malignant epithelial OC and only in a small portion of benign tumors, which was consistent with previous reports." (PMID 25516145, 2015).
brain disease (1 paper, 2011). "Therefore, DEP induction of CYP1B1 at the BBB may bioactivate PAHs adsorbed to DEP into genotoxic intermediates that could increase levels of potentially harmful chemicals, which may initiate BBB dysfunction and/or brain disease." (PMID 21867498, 2011).
colorectal (1 paper, 2026). "Mechanistically, CYP1B1 activates the AKT/SP-1 signaling pathway to upregulate GPX4 expression, thereby modulating colorectal carcinogenesis and progression." (PMID 41493849, 2026).
neurological diseases (1 paper, 2023). "A positive correlation between m1A modification and gene expression was observed, and we selected genes related to neurological diseases (Bag3, Csf1, Cyp1b1, Egfr, Flnc, Lox, Mt1, Nid2, Rab3b, and Tubb4a) for analysis, with MeRIP-RT-PCR and qRT-PCR performed to verify this phenomenon." (PMID 37173310, 2023).
CYP1B1 also shares sentences with these, for which no sentence is quoted: aniridia (5 papers); Axenfeld-Rieger syndrome (3); Onset (3); renal fibrosis (3); retinal degeneration (3); skin cancer (3); corneal dystrophies (2); Glucose intolerance (2); hypertrophy (2); inflammatory bowel disease (2); iris hypoplasia (2); left ventricular hypertrophy (2); medulloblastoma (2); mucositis (2); myopia (2); Peters anomaly (2); vitamin D deficiency (2); abdominal aortic aneurysm (1); Allergy (1); Anophthalmia (1); anterior segment dysgenesis (1); aortic aneurysm (1); Arnold-Chiari malformation type II (1); astrocytoma (1); benign breast disease (1); Best vitelliform macular dystrophy (1); candidiasis (1); carcinoma of the endometrium (1); cardiomyopathy (1); cerebellar ataxia (1).
A further 66 diseases each share a sentence with CYP1B1 in 1 paper.